ENSG00000278778
Gene: Miscellaneous RNA gene on chromosome 4 (3,063,472 to 3,063,701, forward strand). Ensembl gene ENSG00000278778.
Gene Ontology:
Biological process: regulation of gene expression